EGFR (epidermal growth factor receptor)
Diseases named in the same sentence as EGFR in open-access papers (continued):
Sharing a sentence is not in itself a finding about the gene and the disease.
tumor (continued). "Factors such as ALK rearrangements and EGFR mutations, patient-specific characteristics, genetic changes, treatment modalities, and tumor heterogeneity significantly impact the disease's progression and response to therapy, thereby affecting survival rates." (PMID 39850198, 2024). "Third, male sex, tumor size ≤ 2 cm, transfissural approach, and EGFR-TKIs combined with chemotherapy were independent risk factors for rebiopsy complications." (PMID 38803532, 2024). "In the present work, we demonstrated that EGFR mutations enhance the tumor expression of TGF-β, which contributes to the suppression of CD8+ T cell infiltration, proliferation, and cytotoxicity in the TME." (PMID 39004699, 2024). "EGFR was mutated in 5/17 (29%) patients; one patient showed exon 19 deletion and another patient had EGFR and Tumor Supressor-53 (TP-53) mutation." (PMID 39449814, 2024). "We also aimed to elucidate the dynamic changes and functions within the tumor immune microenvironment associated with resistance to TKIs in EGFR-mutant NSCLC." (PMID 39638994, 2024). "Overexpression and mutation of EGFR are associated with poor prognosis and tumor progression in non-small cell lung cancer (NSCLC)." (PMID 38927911, 2024). "EGFR mutations are usually detected from tumor DNA in the form of formalin-fixed paraffin-embedded (FFPE) diagnostic blocks or ctDNA from plasma." (PMID 39066920, 2024). "Among these, we found 4771 patients whose tumor had an EGFR mutation, including 1474 with EGFR L858R." (PMID 38182677, 2024). "In the presence of secondary mutations in EGFR or activation of bypass networks, EGFR-TKIs fail to suppress canonical cancer-signaling pathways, resulting in tumor cell proliferation." (PMID 39456595, 2024). "Several studies have demonstrated the cobas EGFR mutation test v2 to be superior over other qPCR-based tests in molecular analysis of EGFR mutations in tumor tissue and liquid biopsy." (PMID 39063150, 2024). "The WES-based study provides additional insight to understand the drug resistance mechanisms driven by tumor mutations and helps develop potential lead compounds to inhibit EGFR in the presence of drug resistance mutations." (PMID 39130636, 2024). "There is emerging evidence that the presence of this mutation indicates tumor sensitivity to classic EGFR-targeting inhibitors, in contrast to other EGFR exon 20 insertion subtypes." (PMID 38398169, 2024). "Epidermal growth factor receptor mutation in peripheral blood and tumor tissues is highly consistent in patients with NSCLC." (PMID 39634906, 2024). "One patient with an EGFR exon 21 (L858R) mutation had 30% residual viable tumor cells in the resected tumor, and another patient with an ERBB2 mutation had 70% residual viable tumor cells post-induction therapy." (PMID 39349061, 2024). "As monotherapy with BRAF V600E inhibitors has been shown to cause activation of EGFR, which in turn causes tumor proliferation, current therapeutic options associate BRAF inhibitors with EGFR antibodies." (PMID 39682117, 2024). "Tumor heterogeneity, in particular looking at EGFR mutations, is currently under investigation to further correlate cellular modifications with therapeutic response." (PMID 38893088, 2024). "EGFR amplification and overexpression are commonly observed in EC, with mutations in this receptor significantly contributing to tumor progression and invasion." (PMID 39415846, 2024). "Although a correlation between tumor location and EGFR mutation was observed, further investigation is warranted due to the limited number of tumor specimens from the right lobe of the lung." (PMID 38980474, 2024). "The focus has shifted to detecting driver genes associated with tumor development, such as EGFR, KRAS, and MET, and identifying the signaling pathways of cell growth or apoptosis regulated by these genes." (PMID 39144829, 2024). "It is well-established that EGFR and its associated pathways significantly contribute to tumor progression." (PMID 39628999, 2024).
tumor (continued). "Tumor cells harboring classic variants are highly sensitive to first-, second-, or third-generation EGFR tyrosine kinase inhibitors (TKIs)such as erlotinib, gefitinib, afatinib, Furmonertinib,and osimertinib,etc." (PMID 38774882, 2024). "Ultra-deep sequencing was thus performed to detect a drug-sensitive EGFR mutation in the patient’s tumor cells." (PMID 38398169, 2024). "EGFR-tyrosine kinase inhibitors (TKIs) have demonstrated significant efficacy in eliciting tumor responses, particularly in NSCLC patients with EGFR mutations, surpassing traditional cytotoxic chemotherapy regimens." (PMID 39743996, 2024). "EGFR mutation elevates the expression of hypoxia-inducible factor-1 alpha to upregulate the production of glycolytic enzymes, increasing glycolysis and tumor resistance." (PMID 38255882, 2024). "In this study, the plasma samples from the NSCLC patients were paired with tissue samples, and the analysis of EGFR mutation in tumor tissue was considered the gold standard." (PMID 38806596, 2024). "Compared with wild-type tumors, tumors with EGFR mutations show more heterogeneity in the expression level of programmed cell death ligand 1 (PD-L1), tumor mutational burden (TMB), and other tumor microenvironment (TME) characteristics." (PMID 38163979, 2024). "Male sex, tumor size ≤ 2 cm, transfissural approach, and the use of EGFR-TKIs combined with chemotherapy were independent risk factors for complications even after multivariate analysis." (PMID 38803532, 2024). "In analysis of radiological features, the patients with EGFR mutation were significantly associated with bigger size of tumor, lobulation, air-bronchogram, bubblelike lucency and pleural retraction, and this observation aligned with formerly released studies." (PMID 38528507, 2024). "Not all tumor cells contain the same genetic alterations, and EGFR mutations are only observed in a subset of tumor cells." (PMID 39358807, 2024). "Based on the results of the ADAURA trial, if a patient's tumor is found to harbor an EGFR mutation, adjuvant treatment with osimertinib should be offered for 3 years as part of the systemic treatment." (PMID 38530556, 2024). "Another age‐associated genetic difference is the absence or very rare frequency of EGFR mutations in children as compared to adult tumours." (PMID 38299304, 2024). "Resistant tumor cell populations can either already be present before therapy or develop later by biochemical adaptations or new genomic mutations in the EGFR pathway." (PMID 39000238, 2024). "EGFR expression is also associated with poor tumor differentiation, ER negativity, a higher mitotic index, and decreased survival." (PMID 39405290, 2024). "When the allele frequency of EGFR mutations is low, other pathways are more likely to be involved in tumor pathogenesis." (PMID 39358807, 2024). "EGFR is a receptor tyrosine kinase inhibitor, and its overactivation is associated with tumor progression and immune evasion." (PMID 38972967, 2024). "Beyond cellular analysis, advancements in molecular imaging, such as PET scans using specific tracers designed to target mutant proteins, are under investigation, potentially allowing direct visualization of EGFR mutations within tumor sites." (PMID 39834943, 2024). "Despite the predictive effect of the PD-L1 biomarker, there are still several limitations to its practical use, including variation over time and tumor locations, inconsistent prediction efficacy, and unclear interactions with EGFR and ALK mutations." (PMID 39350284, 2024). "Due to procedural and technical advantages of liquid biopsy, it has been widely accepted as an alternative to tumor tissue genotyping for detecting EGFR mutations in NSCLC." (PMID 39066920, 2024).
tumor (continued). "Gene testing was performed on the tumor specimens from 9 patients, and all of them (9/9) were EGFR mutation-positive." (PMID 38637495, 2024). "This binding effectively inhibits the autophosphorylation of the EGFR, resulting in a more sustained blockade of the signaling pathways associated with tumor growth." (PMID 39518531, 2024). "The approach to treating EGFR exon 19 deletion, L858R point mutation, and T790M mutation has advanced personalized drug therapy based on tumor genotyping, moving away from a one-size-fits-all approach." (PMID 38927911, 2024). "The molecular profile of this tumor includes pathogenic polymorphisms in the epidermal growth factor receptor (EGFR), TERT promoter, and 7 and 10 chromosomal alterations." (PMID 39768176, 2024). "The in vivo efficacy of the mRNA-encoded bispecific antibodies was evaluated in xenograft tumor models expressing EGFR." (PMID 39835115, 2024). "Upregulated EGFR expression in BC patients is associated with increased tumor development and resistance to apoptosis, indicating a more aggressive disease phenotype." (PMID 39057437, 2024). "Gefitinib is a first-generation, orally bioavailable, competitive, reversible EGFR TKI that interferes with tyrosine kinase signaling in tumor cells with mutated and hyperactive EGFR." (PMID 39272847, 2024). "For example, the combination of PD-1/L1 blockade and inhibition of CD73, IL-6, ILT4, PKCδ, or CD55/CD59 has been shown to inhibit EGFR-mutated tumor growth in animal models." (PMID 39004699, 2024). "The results of mIF showed that the H-scores of TGF-β1 (P = 0.0055), TGF-β2 (P = 0.0172), and TGF-β3 (P = 0.0080) were significantly higher in EGFRΔ19-mutated tumor tissue than in EGFR WT tumors." (PMID 39004699, 2024). "EGFR–TKIs resistance is a major cause for tumor recurrence and therapeutic failure in EGFR-mutant NSCLC." (PMID 39090096, 2024). "There were three patients with EGFR-mutated tumors (arm A: EGFR insertion exon 20; arm B: EGFR deletion exon 19 and co-mutation of EGFR p.G719A and p.S768I), who had 95% (arm A) and 50% viable tumor cells (both in arm B) following study therapy." (PMID 38689060, 2024). "Recent molecular data on YA-OCSCC suggests a potential profile characterized by epidermal growth factor receptor overexpression, low tumor mutation burden and an attenuated immune response." (PMID 39421447, 2024). "In EGFR-mutated NSCLC, the lower efficacy of immunotherapy can be attributed to the significantly lower tumor mutation burden (TMB) compared to that in EGFR wild-type NSCLC." (PMID 39165617, 2024). "More importantly, we integrated the tumor-informed personalized MRD technique to longitudinally monitor the treatment efficacy of neoadjuvant treatment in patients who all bore specific EGFR mutations." (PMID 38897205, 2024). "Tumor somatic mutation analysis from a peripheral blood sample using Guardant360 showed EGFR exon 19 deletion, with a high allelic frequency of 25%, EGFR amplification, and ESR1 mutation." (PMID 38957515, 2024). "In cancers, core fucosylation of EGFR is associated with increased dimerization and phosphorylation, which leads to an increase in EGFR-mediated signaling related to tumor cell growth and malignancy." (PMID 39777265, 2024). "Although it is certain that TB can induce EGFR mutation and increase the risk of tumor development, the exact molecular mechanism remains to be further elucidated." (PMID 38298194, 2024). "Results from the AURA clinical trials underlined the use of ctDNA analysis in reflecting tumor heterogeneity, monitoring the efficacy of EGFR TKIs as well as the early detection of resistance mechanisms." (PMID 39497713, 2024). "Specifically, the EGFR mutations appeared of significant relevance with patients with lung mix ground glass nodules (p<0.01) and those with larger tumor diameters (p<0.01)." (PMID 38528507, 2024).
tumor (continued). "The study found that tumor PD-L1 expression was more common among patients with wild-type EGFR than those mutated for EGFR (51.3% vs 48.7%, P < .001)." (PMID 38394518, 2024). "This aberrant activity is driven by various oncogenic pathways and dysfunctions in tumor suppressors, including mutated or amplified EGFR, PI3K, Akt, Ras, and Raf, as well as impaired PTEN, APC, LKB1/STK11, and Gator1." (PMID 38560690, 2024). "The patient was given gefitinib at 250 mg/qd as a first-line treatment after identification of the epidermal growth factor receptor (EGFR) L858R mutation in a tumor biopsy sample using the amplification-refractory mutation system." (PMID 38204337, 2024). "EGFR abnormalities, driven by amplification or the EGFRvIII mutation, are linked to higher tumor malignancy and poorer prognosis." (PMID 39184354, 2024). "This study demonstrated the correlations between tumor features, age at diagnosis, and EGFR mutation rates of GGOs." (PMID 39722087, 2024). "For BRAF V600E-mutated tumors, combining encorafenib with anti-EGFR agents such as cetuximab has shown promise, as this approach disrupts multiple signaling pathways that contribute to tumor growth and chemotherapy resistance." (PMID 39684219, 2024). "EGFR is overexpressed in several tumors and is associated with tumor epithelial-mesenchymal transition (EMT), migration, and invasion." (PMID 40051976, 2024). "Our study also showed that EGFR amplification was significantly associated with high-grade histology, tumor necrosis, and high tumor content." (PMID 38687753, 2024). "The molecular characteristics of this novel tumor type make EGFR a potential diagnostic and prognostic biomarker." (PMID 38893240, 2024). "Other tumor-associated antigens identified in pediatric brain tumors (PBTs), including B7-H3, EGFR, Herceptin-2 (HER2), disialoganglioside 2 (GD2), are in clinical testing." (PMID 38785789, 2024). "Integrins, such as α5β1, can either directly or indirectly associate with growth factor receptors such as EGFR, to promote intracellular signaling leading to tumor growth and invasion." (PMID 38315147, 2024). "Tyrosine kinase inhibitor (TKI) sensitizing EGFR mutations were discovered via DNA analysis of tumor tissues obtained from responders to gefitinib or erlotinib." (PMID 38966170, 2024). "EGFR hyperactivation is a hallmark of numerous human tumors, where it drives Ras signaling to promote tumor proliferation and survival." (PMID 39772250, 2024). "A study investigating ctDNA as a substitute for invasive tumor biopsy linked EGFR mutation in ctDNA to cancer prognosis." (PMID 39239557, 2024). "This trial specifically focused on patients with PD-L1 expression levels of ≥1% on tumor cells or immune cells, excluding those with EGFR mutations or ALK translocations." (PMID 39199653, 2024). "EGFR mutations can be detected in plasma as circulating tumor DNA (ctDNA), a technique also known as liquid biopsy." (PMID 38593164, 2024). "The dynamic nature of tumor genetics, exemplified in this case by the evolution from an EGFR mutation to an additional MET amplification, underscores the necessity of repeated genetic assessments." (PMID 39193383, 2024). "Among the key targets are the tumor associated antigens, like EGFR, which has been broadly used in clinical." (PMID 39192980, 2024). "Accumulating evidence shows that EGFR upregulation is significantly associated with tumor development and indicates poor prognosis in UM." (PMID 38686044, 2024). "The irreversible bond inhibits EGFR kinase phosphorylation and activation of downstream tumor signaling pathways and induces EGFR-mutated cells to degrade." (PMID 38414743, 2024). "In a phase IIB trial comparing afatinib and gefitinib for first-line treatment in common EGFR mutation metastatic adenocarcinoma patients, afatinib demonstrated a significantly higher objective tumor response rate compared to gefitinib (70% vs. 56%)." (PMID 39055566, 2024).
tumor (continued). "It has been reported that VT3989 combined with osimertinib has strong synergistic anti-tumor effects against several EGFR-mutated NSCLC cell lines." (PMID 38499647, 2024). "The effectiveness of using KRAS mutation status from the primary tumor alone to predict response to anti-EGFR agents remains a subject of ongoing debate." (PMID 39064004, 2024). "First of all, presence of rare mutations rendering tumor responsiveness to conventional EGFR TKIs (gefitinib, erlotinib, afatinib, osimertinib, etc.)cannot be reliably excluded using mutation-specific PCR." (PMID 38966170, 2024). "EGFR represents a prominent example of a well-established tumor-associated antigen that is broadly expressed at low levels in healthy tissues." (PMID 38492569, 2024). "In our study, targeted NGS assay and the single-gene qPCR test showed 76.14% concordance rate (Cohen’s Kappa = 0.60) in detection of actionable EGFR variants in clinical tumor tissue specimens from 59 advanced NSCLC patients." (PMID 39063150, 2024). "Particularly, patients with brain metastasis and those harboring EGFR amplification or high tumor mutation load gained significant more benefits in PFS from gefitinib plus anlotinib." (PMID 39134529, 2024). "This antibody binds to an epitope of EGFR exposed only on tumor cells with an overexpressed or mutated receptor (EGFRvIII), while it is almost inactive on healthy tissues." (PMID 39000238, 2024). "Elevated expression of EGFR in tumor tissue has been linked to diminished rates of recurrence-free survival or overall survival." (PMID 38672614, 2024). "In the present study, the results of case NCCLu-157, in which the patient’s tumor cells harbored the EGFR A763_Y764ins mutation, were consistent with previous reports." (PMID 38398169, 2024). "They found the KRAS mutation in 39.8% of patients and that the KRAS mutation showed a correlation with the expression of the EGFR gene, primary tumor site, and multiple metastases." (PMID 39125664, 2024). "Studies have reported that EGFR overexpression is associated with a higher nuclear grade (p < 0.001), a larger tumor size (p = 0.011), and a shorter patient survival (p = 0.046)." (PMID 38893126, 2024). "Among them, EGFR mutations can inhibit tumor immune response through various mechanisms, such as reducing the number and function of antigen-presenting cells, decreasing T-cell infiltration and activation, and increasing the number of immunosuppressive cells." (PMID 38938778, 2024). "The presence of a sensitizing EGFR mutation in a tumor is the strongest biological predictor of sensitivity to an EGFR TKI." (PMID 39497876, 2024). "Constitutive activation of EGFR drives growth-promoting effects in tumor cells, with RAS protein mutations, in particular, leading to sustained, receptor-independent activation of downstream RAF proteins." (PMID 38730642, 2024). "EVs released by cancer cell lines such as A549, HepG2, MCF10A, and MCF-7 prolonged monocyte survival, prompting the development of tumor-associated macrophages (TAM) via the transfer of phosphorylated EGFR, thus promoting an inflammatory microenvironment." (PMID 39697631, 2024). "The tumor specimens with neoplastic cellularity ≥50% showed significantly higher EGFR variant read frequencies (median 35.00; min–max: 2.46–92.82) than the specimens with cellularity <50% (19.39; 2.44–87.16; p = 0.0040)." (PMID 39063150, 2024). "In many hostile tumours, the highly expressed genes is EGFR which is associated with tumour growth and invasion." (PMID 39434198, 2024). "Male sex, tumor size ≤ 2 cm, transfissural approach, and EGFR-TKIs combined with chemotherapy were independent risk factors for rebiopsy complications." (PMID 38803532, 2024). "Three mutations were detected in both tumor and plasma samples for the same female: EGFR p.E746_A750del (sample number 40), KRAS p.G12A (sample number 48), and EGFR p.L747_P753delins (sample number 50)." (PMID 38730722, 2024).